ABCG2 (ATP binding cassette subfamily G member 2 (JR blood group))
Diseases named in the same sentence as ABCG2 in open-access papers (continued):
Sharing a sentence is not in itself a finding about the gene and the disease.
gallbladder carcinoma (4 papers, 2017 to 2024). "Emodin was also reported as a strong inhibitor of P-glycoprotein in the MDR1-transfected Madin–Darby Canine Kidney II (MDR1-MDCK II) and Caco-2 cells (IC50=9.42 μM), and inhibited the expression of the ATP-binding cassette super-family G member (ABCG2) in gallbladder carcinoma." (PMID 36830331, 2023). "In contrast, in the human gallbladder cancer cell line GBC-SD, following treatment the SP cells showed upregulated ABCG2 expression and increased drug resistance." (PMID 36831452, 2023).
Hyperglycemia (4 papers, 2012 to 2018). An increased concentration of glucose in the blood. "Higher IC50 levels were detected in HNSCC cells treated with prolonged hyperglycemia suggesting that high glucose inputs could protect HNSCC cells from cisplatin-mediated cytotoxicity, probably via significant increased expression of the drug-resistant mediator ABCG2 mRNA." (PMID 26337468, 2015).
invasive breast carcinoma (4 papers, 2017 to 2025). A carcinoma that infiltrates the breast parenchyma. "Previous studies confirmed the elevation in ABCG2 gene and protein expression levels in patients with neoadjuvant chemotherapy and invasive breast cancer." (PMID 37166017, 2023).
kidney failure (4 papers, 2012 to 2021). An acute or chronic condition that is characterized by the inability of the kidneys to adequately filter the blood. "Several studies have reported that the mRNA and protein expression of OATs or ABCG2 was reduced in various renal failure rats." (PMID 33790363, 2021). "Animal studies demonstrated that Abcg2 expression in the ileum of 5/6 nephrectomized/kidney failure (characterized by significant, twofold increase in creatinine serum concentrations and respective twofold decrease in creatinine clearance) rats was significantly increased." (PMID 32715435, 2020).
laryngeal carcinoma (4 papers, 2013 to 2023). Carcinoma that arises from the laryngeal epithelium. "It has been previously suggested that the abnormal expression of ABCG2 may be related to the invasion and metastasis of laryngeal carcinoma, thus providing a good reference basis for the evaluation of LSCC invasivity." (PMID 35681602, 2022). "Last, but not least, the presence of p75ICD (but not p75NTR FL) in CSCs surrounded by what is reminiscent of ABCG2-positive extracellular vesicles suggests a role for p75ICD in drug resistance, a major factor limiting the efficacy of chemotherapy in patients with laryngeal cancer." (PMID 35681602, 2022).
mesothelioma (4 papers, 2015 to 2024). A usually malignant and aggressive neoplasm of the mesothelium which is often associated with exposure to asbestos. "For KIRC and SARC, female patients show higher ABCG2 expression, in contrast to mesothelioma (MESO) and LIHC, where male patients show higher ABCG2 expression." (PMID 36555598, 2022). "Similarly, dactolisib reversed drug resistance mediated by ABCB1 and ABCG2 in AML and mesothelioma cell lines, respectively." (PMID 37048130, 2023).
metastatic melanoma (4 papers, 2012 to 2020). A melanoma that has spread from its primary site to another anatomic site. "Interestingly, ABCG2 has been reported to be expressed in the majority of metastatic melanoma tissue specimens and its levels of expression correlated with patient survival." (PMID 29330434, 2018). "Inconsistently with findings published by Fang’s group, CD133+ D10 cells had not upregulated the expression of ABCG2 (ATP-binding cassette, sub-family G (WHITE), member 2A), which was identified to be overexpressed in primary or metastatic melanoma compared to benign melanocytic nevi." (PMID 23915418, 2013).
nephrolithiasis (4 papers, 2014 to 2023). The presence of a calculus in the pelvis of the kidney; this is most often composed of mineral salts and proteins. "A similar distribution of the ABCG2 rs2231142 variants in the male population with nephrolithiasis was observed, with TT and GT genotypes occurring more frequently in participants with nephrolithiasis (p<0.001)." (PMID 36967798, 2023). "In this study, we aimed to explore the association between ABCG2 rs2231142 variant and the risk of nephrolithiasis in a community-based Taiwanese population." (PMID 36967798, 2023). "We aimed to investigate the interaction between the ABCG2 rs2231142 variant and incident nephrolithiasis in the Taiwanese population." (PMID 36967798, 2023). "Association of demographics, comorbidities, ABCG2 rs2231142 variants, and lifestyle factors with the risk of nephrolithiasis." (PMID 36967798, 2023). "Associations of the ABCG2 rs2231142 variant with serum uric acid levels, and the incident nephrolithiasis were explored." (PMID 36967798, 2023). "Our study is the first to reveal that the risk of nephrolithiasis was markedly increased in participants with the ABCG2 rs2231142 T genotypes." (PMID 36967798, 2023). "In this study, we confirmed the importance of the ABCG2 rs2231142 variant with which the risk of nephrolithiasis is significantly associated." (PMID 36967798, 2023). "Sex-stratified risk of nephrolithiasis with the ABCG2 rs2231142 genotypes." (PMID 36967798, 2023). "Further investigations are needed to elucidate the pathogenesis of ABCG2 in nephrolithiasis." (PMID 36967798, 2023). "ABCG2 genetic variation is a significant risk of nephrolithiasis, independent of serum uric acid levels." (PMID 36967798, 2023). "Additional factors, such as sequence variation in other UA transporters (SLC22A12, SLC17A3, ABCC4 and ABCG2), age, sex, diet, drugs, physical activity, environment and volume status can influence the degree of UA tubular absorption and the risk of EIARF or nephrolithiasis." (PMID 24397858, 2014). "However, it is unclear whether the ABCG2 gene contributes to the development of nephrolithiasis." (PMID 36967798, 2023).
prostate tumor (4 papers, 2013 to 2026). "Alternatively, there could be cancer stem cells expressing different markers, other than ABCG2 or ALDH activity, that have the capability to initiate prostate tumor growth." (PMID 24405526, 2013).
tongue squamous cell carcinoma (4 papers, 2015 to 2020). A squamous cell carcinoma that arises from the tongue. "In contrast miRNA-222 mimics can promote sensitivity to cisplatin in tongue squamous cell carcinoma by reducing expression of ABCG2." (PMID 31979312, 2020). "Interestingly, ABCG2 is epigenetically regulated by miR-222 in tongue squamous cell carcinoma, and deregulation of the miR-222–ABCG2 contributes to cisplatin resistance, and cancer aggressiveness." (PMID 28704968, 2017).
Anxiety (3 papers, 2012 to 2019). Intense feelings of nervousness, tension, or panic often arise in response to interpersonal stresses. "The present findings raise the question of whether ABCB1 and ABCG2 polymorphisms might explain genetic susceptibility to cannabis-induced psychosis or the adverse psychoactive effects of this drug (e.g. addiction, anxiety and cognitive impairment) by altering the brain disposition of THC." (PMID 22536451, 2012).
cardiac hypertrophy (3 papers, 2017 to 2025). "In addition, ABCG2 can prevent cardiac hypertrophy and heart failure caused by pressure overload, and suppression of inherent ABCB1 elevates the susceptibility to doxorubicin-induced cardiotoxicity." (PMID 40755506, 2025). "The ATP-binding cassette transporter subfamily G member 2 (ABCG2) mediates protection from cardiac hypertrophy and heart failure under pressure overload via activation of antioxidant response pathways." (PMID 41440040, 2025). "Previous studies in the transverse aortic constriction model showed that mice lacking ABCG2 have reduced angiogenesis in the LV, which was associated with cardiac hypertrophy." (PMID 28270772, 2017). "In addition, ABCG2 protects against pressure overload-induced cardiac hypertrophy and left heart failure and is cardioprotective after myocardial infarction." (PMID 28270772, 2017).
depression (3 papers, 2016 to 2025). "We next explored the expression of ABCG2 using immunohistochemistry in tumors from patients with mild depression and from those with severe depression (n = 10)." (PMID 27852063, 2016). "The results were in agreement with the previous data, and demonstrated that the tumors of patients with severe depression demonstrated stronger expression of ABCG2." (PMID 27852063, 2016).
gastric adenocarcinoma (3 papers, 2019 to 2024). "All these data supported our findings in gastric adenocarcinoma cells that inhibiting ABCG2 activity in cancers with high SLFN11 expression can increase the efficacy of SN-38." (PMID 39033209, 2024). "Accordingly, erlotinib increased the accumulation of ABCG2 substrate Hoechst-33342 in our gastric adenocarcinoma cells, similar to the ABCG2 inhibitors." (PMID 39033209, 2024). "Moreover, the degree of synergism positively correlated with the ABCG2 expression level of gastric adenocarcinoma cell lines, except for SNU16 cells." (PMID 39033209, 2024). "Furthermore, EGFR inhibitors may provide an advantage in highly heterogeneous gastric adenocarcinomas by acting both on cells susceptible to the action on EGFR and cells sensitive to the off-target activity on ABCG2." (PMID 39033209, 2024). "Therefore, our findings suggest that combining ABCG2 inhibitors or EGFR inhibitors with SN-38 or irinotecan could be a promising strategy in gastric adenocarcinoma." (PMID 39033209, 2024). "Our gene knockout and pharmacological inhibition studies also confirmed the off-target inhibition of ABCG2 by erlotinib as the mechanism of synergism with SN-38 in SNU5 cells, derived from a gastric adenocarcinoma patient who previously received chemotherapy." (PMID 39033209, 2024).
gastroenteritis (3 papers, 2016 to 2023). An inflammatory disorder that affects the upper and lower gastrointestinal tract. "Decreased intestinal excretion has been proven not only in Abcg2 knockout mice but also in humans; indeed, both gastroenteritis and hemodialysis patients showed decreased intestinal and renal urate excretion, respectively, in parallel to their ABCG2 dysfunction levels." (PMID 38137389, 2023). "The UA excretion factor ATP-binding cassette transporter G2 (ABCG2), which inhibits UA excretion not only from the kidney but also from the intestine, may fail to function in gastroenteritis." (PMID 37123782, 2023).
Hyperinsulinemia (3 papers, 2019 to 2024). An increased concentration of insulin in the blood. "When IR occurs, acute physiological hyperinsulinemia can stimulate urate reabsorption by regulating the expression of URAT1 and ABCG2." (PMID 33014043, 2020).
Immunodeficiency (3 papers, 2013 to 2023). Failure of the immune system to protect the body adequately from infection, due to the absence or insufficiency of some component process or substance. "In order to evaluate the tumorigenicity of ABCG2+ versus ABCG2− cells, we inoculated subcutaneously 8 × 103, 4 × 104, 2 × 105, 1 × 106, and 5 × 106 ABCG2+ SMMC-7721 cells and the same amount of ABCG2− cells into immunodeficiency mice, respectively." (PMID 24194752, 2013).
invasive ductal carcinoma (3 papers, 2011 to 2021). "HIF-2a was correlated with ABCG2 expression, histology-grade and Ki67 expression in breast invasive ductal carcinoma." (PMID 22452996, 2012). "The results showed that ABCG2 was expressed in different intensities and distributions in the tumor cells of the breast invasive ductal carcinoma." (PMID 21943250, 2011). "Our study demonstrates the expression of ABCG2 in normal ductal epithelia and in the tumor cells of invasive ductal carcinoma of breast." (PMID 21943250, 2011). "In the cells of the breast invasive ductal carcinoma, ABCG2 expression was present in different intensities and different cell distributions." (PMID 21943250, 2011).
kidney cancer (3 papers, 2017 to 2023). Primary or metastatic malignant neoplasm involving the kidney. "A number of the identified transporters (e.g., SLC22A12/URAT1, SLC22A6/OAT1, SLC22A8/OAT3, ABCG2) are well-established uric acid transporters; this may be clinically important since a number of studies indicate that altered uric acid levels and kidney cancer are associated." (PMID 36230695, 2022). "This will be conducive to further research of ABCG2 at molecular level as well as gene level for the drug resistance in kidney cancer." (PMID 28347288, 2017).
kidney damage (3 papers, 2024 to 2025). "The expression levels of uric acid transport-related genes (UAT, ABCG2, and OAT1) in kidney tissue were significantly downregulated (p < 0.05), and evident kidney damage was found." (PMID 39949621, 2025).
leukoplakia (3 papers, 2014 to 2023). A white patch or plaque on a mucous membrane that cannot be characterized clinically or pathologically as any other disease. "A recent long-term follow-up study of 135 patients associated two stem cell markers, ATP-binding cassette G2 subfamily (ABCG2) and Bmi-1 with transformation of oral leukoplakia to cancer." (PMID 24415717, 2014).
liver diseases (3 papers, 2012 to 2025). "The results demonstrated that urate levels mediated by ABCG2 genetic variants exhibited causal effects on multiple liver diseases." (PMID 40282409, 2025). "Subsequently, we employed a drug-target Mendelian randomization analysis to estimate the causal relationship between ABCG2 variant-mediated uric acid levels and liver diseases." (PMID 40282409, 2025). "Our study aimed to elucidate the causal role of ABCG2 genetic variants in modulating urate levels and their impact on liver diseases, including HCC, CCA, and liver fibrosis." (PMID 40282409, 2025). "Notably, only SNPs demonstrating simultaneous associations with both SUA levels and liver diseases were included, with variants within ±100 kb of ABCG2 coding regions, prioritized to account for potential linkage disequilibrium with the neighboring genes." (PMID 40282409, 2025). "The up-regulation of ABCG2 observed in response to drug therapy underlines the importance of this transporter to account for the drug resistance and points the needs to explore its expression in liver diseases, HCC in particular." (PMID 23153066, 2012). "Our findings demonstrated an higher expression of the ABCG2 in liver diseases compared to normal tissue and possibly more important, in HCC where the genetic and functional up-regulation is more marked in less differentiated tumors." (PMID 23153066, 2012).
preeclampsia (3 papers, 2021 to 2025). Preeclampsia is a hypertensive disorder of pregnancy that is characterized by new-onset hypertension with proteinuria presenting after 20 weeks of gestation, and depending on mild or severe forms may initially present with severe headache, visual disturbances, and hyperreflexia. "Expression of the breast cancer resistance protein (BCRP/ABCG2) transporter is downregulated in placentas from women with preeclampsia (PE) and in an immunological rat model of PE." (PMID 39065581, 2024). "The most relevant targets for preeclampsia were: AR, VDR, SLC6A2, NOS3 and CHRM4, while ABCG2, ERBB2, CES1 and REN led to the most relevant off-targets." (PMID 33546161, 2021).
renal failure (3 papers, 2012 to 2025). "It is noteworthy that the Ckidney, 4 hr of endogenous IS in febuxostat-administered intact rats was higher than that in the vehicle-administered adenine-induced acute renal failure rats, indicating that febuxostat largely inhibited IS transport from the epithelial cell to lumen via ABCG2." (PMID 33790363, 2021). "The effects of these agents were reduced in adenine-induced acute renal failure rats, presumably due to substantial decrease in renal OAT1/3 and ABCG2 expression." (PMID 33790363, 2021). "Therefore, adenine-induced acute renal failure rats can be regarded as OAT1/3 and ABCG2 down-regulation model." (PMID 33790363, 2021).
serous ovarian cancer (3 papers, 2019 to 2021). "Furthermore, we showed that 4-MU inhibited expression of HAS2, HAS3 and CSC markers (ALDHA1 and ABCG2) in a 3D-spheroid culture of chemoresistant primary serous ovarian cancer cells." (PMID 31443261, 2019). "In addition, in serous ovarian cancer, SIK3 expression is inversely correlated to ABCG2 expression, and patients with low SIK3 and high ABCG2 expression have worse prognosis than patients with high SIK3 and low ABCG2 expression." (PMID 31762812, 2019).
tongue cancer (3 papers, 2015 to 2022). A malignant neoplasm affecting the tongue. "Additionally, it has been reported that ABCG2 expression is deregulated in tongue cancer and significantly associated with regional lymph node metastasis and local recurrence." (PMID 26517090, 2015). "We obtained mechanistic data from EpCAM+/ABCG2+ CSCs of SCC-25 tongue cancer cell line but did not include equivalent primary CSCs in the study." (PMID 36248858, 2022). "However, reduced expression levels of ADLH/A1 and ABCG2 stemness markers were only found in UBE2C-knockdown Ca9-22 cells but not in UBE2C-knockdown SAS cells, which indicating that UBE2C might play a more important role in cancer stemness in tongue carcinoma." (PMID 32899896, 2020).
uterine corpus endometrial carcinoma (3 papers, 2022 to 2026). A endometrial carcinoma (disease) that involves the body of uterus. "We observed a significant positive correlation between the ABCG2 mutation site and prognosis in uterine corpus endometrial carcinoma (UCEC) patients." (PMID 36555598, 2022). "Out of these, mutations observed in uterine corpus endometrial carcinoma were taken into account for further analysis, which narrowed down to a total of 248 mutations: 118 in ABCB1, 82 in ABCC1, and 48 in ABCG2." (PMID 38766631, 2024). "We discovered that p38/MAPK14 was one of the most strongly correlated genes with ABCG2 in patients with BRCA, OV, cervical squamous cell carcinoma, and endocervical adenocarcinoma, uterine corpus endometrial carcinoma, and uterine carcinosarcoma." (PMID 41541684, 2026).
anemia (2 papers, 2018 to 2024). A reduction in the number of red blood cells, the amount of hemoglobin, and/or the volume of packed red blood cells. "In our study polymorphism p.Gln141Lys (rs2231142) in ABCG2 gene was another high risk factor of FAC-induced anemia." (PMID 29507678, 2018). "The variation in another of ABC transporters gene, ABCG2, was also responsible for early anemia, seen in two first courses of treatment." (PMID 29507678, 2018).
atrial fibrillation (2 papers, 2021 to 2025). A disorder characterized by an electrocardiographic finding of a supraventricular arrhythmia characterized by the replacement of consistent P waves by rapid oscillations or fibrillatory waves that vary in size, shape and timing and are accompanied by an irregular ventricular response. "Finally, in 2020, Gulilat’s study of 358 Caucasian patients with atrial fibrillation demonstrated the relationship between the ABCG2 421C > A variant (resulting in impaired transporter function) and higher peak and trough blood levels of apixaban." (PMID 33440670, 2021).
autoimmune disease (2 papers, 2021 to 2023). A disorder resulting from loss of function or tissue destruction of an organ or multiple organs, arising from humoral or cellular immune responses of the individual to their own tissue constituents. "Previous studies have revealed the influence of various SNPs on the toxicity of MTX in patients with autoimmune diseases, such as MTHFR, MTR, ABCC1, ABCC2, and ABCG2." (PMID 37761008, 2023).
cerebral amyloid angiopathy (2 papers, 2013 to 2021). "ABCG2 is up-regulated in human AD brain with cerebral amyloid angiopathy (CAA) where it modulates Aβ-induced vascular oxidative stress." (PMID 23432917, 2013). "In addition, an upregulation of ABCG2 has been found in the brains of AD patients with cerebral amyloid angiopathy, which was also reflected by increased ABCG2 expression levels observed in the RBCs of late-onset AD patients." (PMID 33801813, 2021).